H19 (H19 imprinted maternally expressed transcript)
Diseases named in the same sentence as H19 in open-access papers (continued):
Sharing a sentence is not in itself a finding about the gene and the disease.
tumor (continued). "Furthermore, targeting H19 inhibited tumour metastases by approximately eight-fold in comparison to that of control." (PMID 33126409, 2020). "To investigate whether the inhibition of SNORA7A plays a role in H19-mediated tumor suppression, we performed an in vitro AIG assay and found retarded clonal growth of H19-transduced LFS osteoblasts upon SNORA7A ectopic expression." (PMID 33519915, 2020). "Long non-coding RNA H19 was demonstrated to be significantly correlated with tumor metastasis." (PMID 32698890, 2020). "Importantly, using xenograft MDA-MB-231 tumor-bearing mice, we found that lncRNA H19 was also involved in promoting cancer metastasis." (PMID 32514245, 2020). "Pathological staining analysis of the lymph node samples using HE staining and TNFAIP8 IHC staining also revealed that suppression of lncRNA H19 reduced significantly vacuole and necrosis lesions in lymph node tissues induced by tumor cells, as well as the expression level of TNFAIP8 protein." (PMID 32514245, 2020). "Overexpression of the so-called H19 opposite tumor suppressor (HOTS) could inhibit choriocarcinoma tumor cell growth." (PMID 32429417, 2020). "Furthermore, by exploring its interactions with multiple essential DNA damage/repair response factors, we demonstrate how H19 executes its tumor-suppressive role." (PMID 33519915, 2020). "Additionally, we found that while elevated levels of PIM1 contribute resistance to ADT, the combination of a pan‐PIM‐i and H19 KD can reduce the tumor‐forming capacity of highly aggressive NEPC." (PMID 32146726, 2020). "Furthermore, overexpression of H19 in SMMC-7721 cells inhibits tumor cell invasion by the reversion of EMT." (PMID 32429417, 2020). "The evidence of physical interactions between H19 and DNA damage response genes leads us to speculate that H19 indirectly maintains genomic integrity, explaining its tumor-suppressor activity." (PMID 33519915, 2020). "The tumor development in H19/IGF2:IG-DMR -GOM cases is significantly higher compared to UPD cases." (PMID 33101381, 2020). "However, aberrant expression of H19 and miR675 can influence tumor cell behavior in HCC to remain elusive." (PMID 32485786, 2020). "In TSCC, H19 is demonstrated to be upregulated in the tumor tissue compared with adjacent samples." (PMID 33123473, 2020). "Thus, lncRNAs play diverse roles; for example, H19 can act as either an oncogene or a tumor suppressor in HCC." (PMID 33585204, 2020). "Furthermore, H19 is also reported to be able to promote angiogenesis and tumor inflammation as well as avoid immune suppression." (PMID 33291403, 2020). "On the other hand, H19 is also a precursor of miR-675, and recent studies show that miR-675 promotes tumor progression by repressing twist basic helix-loop-helix transcription factor 1 (Twist1), implying that the proposed oncogenic role of H19 is mediated by the biological function of miR-675." (PMID 32872482, 2020). "An important tumor-related lncRNA H19 was identified to be targeted by NSUN2." (PMID 32978516, 2020). "In addition, in Bel-7402 cells, the apoptosis rate decreases again supporting the idea that H19 works as a tumor suppressor." (PMID 32429417, 2020). "Since PIM1 kinases have been shown to drive the growth of PCa, we sought to address whether the PIM1 regulation of H19 levels was also present in this tumor type." (PMID 32146726, 2020). "In addition, animal models show that H19 inhibition significantly impairs tumor progression and lung metastasis." (PMID 33123473, 2020). "H19 expression is closely related to tumor invasion, metastasis, recurrence and poor prognosis." (PMID 33371204, 2020).
tumor (continued). "Taken together, these results suggest a potential role of SNORA7A in promoting cancer progression and emphasize that H19 tumor suppressor functions may be mediated through the repression of SNORA7A expression." (PMID 33519915, 2020). "It is well known that H19 is considered as a regulatory RNA, which involves in numerous biological processes of human diseases, ranging from transcriptional and post‐transcriptional regulation to tumour suppression and oncogenesis." (PMID 32281297, 2020). "H19 coordinates EMT (epithelial mesenchymal transition) to promote tumor metastasis." (PMID 33193379, 2020). "Besides miR-194-5p, H19 also possesses the ability to sponge miR-342-3p, another established tumor-suppressive miR." (PMID 32331331, 2020). "Another study reported H19 lncRNA mediated cancer initiation, progression and metastasis, indicating that H19 lncRNA could be used as a potential tumour marker for ATC." (PMID 33126409, 2020). "H19, a LncRNA located on chromosome 11p15.5, is abnormally expressed in various tumours." (PMID 33145980, 2020). "The potential function of H19 as a tumor-suppressor or as an oncogene is strongly debated." (PMID 32429417, 2020). "The univariate analyses displayed that higher H19, miR‐130a‐3p, and miR‐17‐5p expressions were more frequently observed within subjects that were featured by bigger tumor size (>5 cm), invasive serous layer, metastatic lymph nodes, and III+IV stages of TNM (P < 0.05)." (PMID 30843379, 2019). "H19 expression in EC tissues was noted to progressively increase with tumor grade." (PMID 30781521, 2019). "The product of the H19 gene is a long non-coding RNA that acts as a tumor suppressor." (PMID 30934541, 2019). "H19 is a well-known and extensively explored lncRNA in regulating tumor activities." (PMID 31632488, 2019). "The preclinical xenograft tumor assays in nude mice indicated that H19 could be a potential target to reverse tamoxifen resistance." (PMID 31340867, 2019). "In the present study, assessment of the correlation between expression of H19 and clinicopathological characteristics showed that H19 was less expressed in patients whose primary tumor size was 4 cm or more, vascular invasion, distant metastasis before or after diagnosis." (PMID 31791180, 2019). "The expression of H19 in tumor tissues of the xenograft models was confirmed." (PMID 31168355, 2019). "However, numerous investigations point to the contradictory effects of H19 on tumor development, progression, and treatment, and indicate the complexity of H19 functionality." (PMID 31277475, 2019). "In our study, we could validate this model in vivo by showing that targeting H19 using shRNA reduced H19 expression level, strongly reduced tumor burden, and abolished metastasization in a thyroid orthotopic ATC mouse model." (PMID 31299871, 2019). "Among the many lncRNAs, H19 has been identified to be responsible for tumor angiogenesis." (PMID 30948500, 2019). "The detection of H19 to aid patients’ stratification is proposed in several other tumor settings." (PMID 31003545, 2019). "(2015), the aggressive phenotype of BC cells may depend on the increased cell proliferation and migration in vitro, as well as the increased tumor growth and metastasis in vivo by the overexpression of H19/miR‐675." (PMID 30803129, 2019). "To investigate the roles of H19 on tumor growth in vivo, we constructed a subcutaneous tumor model." (PMID 30728351, 2019). "H19 is a non-coding RNA of unknown function, which may have a role in both tumor formation and tumor suppression." (PMID 31143763, 2019). "Interestingly, mesenchymal-like cancer cells and primary CRC tissues show high expression of H19, whereas its stable expression accelerates tumor growth and enhances epithelial–mesenchymal transition (EMT) progression." (PMID 31632922, 2019). "LncRNA H19 has been reported to have key regulatory functions in tumor development and progression." (PMID 31164794, 2019).
tumor (continued). "H19 also acts as a molecular sponge for microRNA let-7, regulating tumor metastasis." (PMID 31340867, 2019). "Among the 40 patients, 34 were evaluable for lncRNA H19 expression analysis in tumor tissue." (PMID 31827510, 2019). "Finally, the mice models also produced larger tumor size and higher tumor weight, when H19, miR‐130a‐3p, or miR‐17‐5p expressions were up‐regulated within them (P < 0.05)." (PMID 30843379, 2019). "Additionally, H19 also participates in tumor metastasis, which includes two converse events, EMT and MET." (PMID 31340867, 2019). "A series of well-known oncogenes including H19, H19-as, Foxn2-as and Hottip function in vitamin D receptor protection against skin cancer formation by helping to maintain the balance between oncogenic and tumor-suppressing lncRNAs." (PMID 31226932, 2019). "Therefore, we suggest H19 is a tumor-promoting lncRNA that endows distant metastatic potential to BC cells." (PMID 31744046, 2019). "We propose that H19 might contribute in more than one way to the EZH2-mediated repression of key anti-tumor genes." (PMID 29643989, 2018). "Furthermore, downregulation of H19 gene expression was recognized as an early event in the formation of several tumor types." (PMID 29703210, 2018). "H19/miR-675 has also been reported to be a tumor suppressor." (PMID 28840253, 2018). "H19 is also one of the major lncRNA genes in cancer, but it has long been a controversy whether it is oncogenic or tumor-suppressive." (PMID 30026672, 2018). "Moreover, H19 overexpression resulted in an increase of tumor sphere-formation capacity in MDA-MB-231 cells, whereas depletion of PDK1 limited this induction." (PMID 29106390, 2018). "However, increased expression of H19 has also been observed in a variety of tumors, suggesting that H19 is, in contrast, essential for tumor growth." (PMID 29703210, 2018). "Finally, we characterized the maternal imprints in the PWS and H19 imprinting centers in the tumor and compared them with patient's fibroblasts and iPSCs derived from them." (PMID 30003711, 2018). "In other cases, H19 has been shown to promote tumour growth in mice." (PMID 29972883, 2018). "In addition, H19 expression clearly differentiates tumor samples from short-term survivors from samples excised from the peritumoral areas of the same patients." (PMID 29643989, 2018). "H19 plays essential roles in tumor proliferation, invasion, apoptosis and angiogenesis." (PMID 30547791, 2018). "In addition, H19 was monoallelically expressed indicating retention of normal imprinting in tumour 37T." (PMID 29912901, 2018). "The H19-mediated tumour growth inhibition appears superior to that of CAB treatment." (PMID 30397197, 2018). "Whether H19 is oncogenic or tumor-suppressive remains controversial, but the majority of reports suggest it provides an oncogenic function in many cancers." (PMID 30619763, 2018). "Second, using both in vitro and in vivo models, we demonstrated that overexpression of H19 suppressed tumour cell growth in vitro and tumour growth in vivo, whereas knockdown of H19 expression promoted tumour cell proliferation in vitro and tumour growth in vivo." (PMID 30397197, 2018). "Furthermore, compared with the tumours from the control EV-infected groups, primary tumours from the H19-infected rats showed greatly reduced 4E-BP1 phosphorylation, whereas S6K1 phosphorylation was not affected much." (PMID 30397197, 2018). "Taken together, H19 seems to act as a tumor suppressor as well as an oncogene in HCC." (PMID 30105249, 2018). "Both oncogenic and tumour-suppressive properties of H19 have been reported in previous studies." (PMID 30397197, 2018). "Together, these results show that the effect of H19-induced tumour suppression is superior to that of CAB treatment, and thus, H19 may be a potential treatment target." (PMID 30397197, 2018). "Many DDX43 related genes were involved in tumor growth, including H19." (PMID 29449695, 2018).
tumor (continued). "When tumours were confirmed by magnetic resonance imaging (MRI), the rats were divided into two groups (n = 4) that were administered either adenovirus expressing H19 or EVs (2 × 108 pfu, via stereotactic pituitary injection)." (PMID 30397197, 2018). "The H19 gene is abundantly expressed in mesoderm- and endoderm-derived tissues at embryonic stage, while it is not expressed in most parts of the body except cardiac and skeletal muscle after birth and is re-expressed in the tumor tissues." (PMID 29416703, 2018). "H19 enhances cell migration in vitro and stimulates tumor metastasis in vivo." (PMID 28793797, 2018). "Interestingly, despite the tumor type, all five tested cell lines that were treated with HDACi showed a stable and/or significant over-expressed level of H19 transcript." (PMID 29561759, 2018). "Long non-coding RNA (lncRNA) H19 is a hot spot in tumor development, progression and metastasis." (PMID 30219045, 2018). "H19 and its mature product miR-675 are significantly over-expressed in HNSCC, leading to higher invasive capability, worse overall survival (OS) and higher risk of tumor recurrence." (PMID 29416703, 2018). "A number of noncoding RNAs such as urothelial cancer associated 1 (UCA1), MALAT1, H19, and plasmacytoma variant translocation (PVT1) have been implicated in the promotion of metastasis of tumour cells, but evidence for a more direct role of these RNAs in this process is still lacking." (PMID 30296263, 2018). "H19 also plays an important and multipronged role in tumor angiogenesis by regulating the production of proangiogenic factors such as angiogenin, fibroblast growth factor 18, prolylcarboxypeptidase, tumor necrosis factor α-induced protein 1, calponin 2, and inhibitor of DNA binding." (PMID 28793797, 2018). "H19 overexpression significantly reduced xenograft tumour burden compared with the control group." (PMID 30397197, 2018). "Similarly, when we checked the clinical association of the lncRNAs screened in the present study in TANRIC database, lncRNAs H19, MEG3 and MALAT1 showed significant association with tumor stage and HOTAIR had a significant association with patient survival." (PMID 29719612, 2018). "In addition, H19 can alter the tumor suppressor miR-200 by increasing histone acetylation via the association with the protein complex hnRNP U/PCAF/RNAPol II." (PMID 30154386, 2018). "In addition, H19 significantly promoted the secondary limited dilution tumor transplantation, whereas PDK1 depletion substantially reversed tumorigenic ability." (PMID 29106390, 2018). "Notably, the anti-diabetic drug, metformin, has been shown to suppress the tumor cell migration and invasion, partly by epigenetic down-regulation of H19." (PMID 27664137, 2017). "H19 is involved in multiple stages of tumor progression including proliferation and metastasis." (PMID 27732939, 2017). "H19 is expressed in the majority of serous epithelial tumors, which may suggest the possible application of this lncRNA as an adjuvant tumor marker in diagnosis, staging, and follow-up of patients with such disorders." (PMID 27664137, 2017). "In addition over-expression of H19-miR675 is frequently observed in colorectal cancers, which suppress the expression of the tumor-suppressor RB18." (PMID 28883545, 2017). "And nude mice injected with H19-transfected cells, develop increasing tumor progression." (PMID 27732939, 2017). "Targeting H19 expression may be a potential therapy, as H19 knockdown in cancer cell lines, such as Hep3B, has been shown to decrease tumor weight and tumor volume." (PMID 28933364, 2017). "Studies reported different, even contradictory, roles of H19 in tumorigenesis in different tumor models, implying that the regulatory role of H19 may be specific to tumor context." (PMID 29273733, 2017). "As continuous tumor growth could be sustained by BCSCs, we performed serial transplantation in nude mice to investigate the in vivo role of H19 in the regulation of BCSC maintenance." (PMID 28102845, 2017).
tumor (continued). "LncRNA H19 in ER-positive breast cancer shows 10 times more than that in ER-negative tumor tissues." (PMID 27732939, 2017). "Whether functional role of H19 is tumor suppressive or oncogenic is still controversy, and it might depend on different cancer types, development stages and molecular background to a large extent." (PMID 28230721, 2017). "Furthermore, H19 depletion significantly repressed the second limited dilution tumor transplantation." (PMID 28102845, 2017). "Besides H19, there are still other transcripts from H19/IGF2 locus including HOTS (H19 opposite tumor suppressor), 91H, PIHit and miR-675." (PMID 28230721, 2017). "H19 participates in the epigenetic regulation of many processes impacting diseases, such as activating the miR-200 pathway by histone acetylation to inhibit the epithelial-mesenchymal transition to suppress tumor metastasis." (PMID 28933364, 2017). "Another lncRNA, H19 could promote tumor metastasis by regulating critical events including the epithelial-to-mesenchymal transition and the mesenchymal-to-epithelial transition." (PMID 29190941, 2017). "Additionally, H19 is also involved in the tumor metastasis, which includes two converse events: the EMT and the MET." (PMID 27732939, 2017). "Although the currently identified targets of miR-675 seem to display a scattered distribution, most of them participate in growth, differentiation and different stages of tumor development, which also suggests an important position of H19 in growth-related gene networks." (PMID 28230721, 2017). "H19 has been shown to bind and inhibit the activity of miRNAs, affecting target gene expression in tumor cells; therefore, we hypothesized that this may be the mechanism through which H19 regulates the expression of EMT-related proteins." (PMID 28327666, 2017). "Besides, tumor-suppressor miR-141 overexpression suppressed osteoblastic cell proliferation by down-regulating lncRNA H19 in OS." (PMID 28720111, 2017). "H19 expression in the tumor microenvironment is of systemic and local significance." (PMID 29088808, 2017). "This assumption may be supported by our observation that circulating tumor cells have very high levels of H19/miR-675 (unpublished data)." (PMID 26623562, 2016). "We propose that that H19/miR-675 axis may function as a tumor suppressor or as an oncogene by at least in part through modulating the differentiation process." (PMID 26623562, 2016). "Furthermore, and most importantly, we consistently detected high H19 expression levels in the invasive front of primary tumor biopsies (reflecting EMT)." (PMID 26623562, 2016). "H19 lncRNA is at the core of multiple signaling pathways that dictate a tumor's deadly signature." (PMID 26623562, 2016). "For instance, plasma H19 may serve as a potential biomarker to diagnose gastric cancer and monitor tumor dynamics for tumor resection." (PMID 27793008, 2016). "This suggests that H19 is expressed at substantial levels in several different tumor types, and might re-activate expression within the process of tumorigenesis." (PMID 27501229, 2016). "H19 is a developmentally regulated gene with putative tumor suppressor activity." (PMID 27317124, 2016). "Furthermore, cells over-expressing H19 can colonize the lung faster and establish much larger tumor foci compared to control." (PMID 26623562, 2016). "H19 is an imprinted gene, first discovered as a tumor suppressor." (PMID 27698357, 2016). "Interestingly, we found that H19/hsa-let-7b/IGF2BP1 competing triplet involved in the tumor state ceRNA network of UCEC." (PMID 27580177, 2016). "Alternatively, H19 has been reported to act as a tumor suppressor in mice in vivo." (PMID 26992233, 2016). "However, the significant increase of H19 during the process of tumor formation in mice was accomplished by injected carcinoma cell lines." (PMID 27501229, 2016).